ESR1 (estrogen receptor 1)
Diseases named in the same sentence as ESR1 in open-access papers (continued):
Sharing a sentence is not in itself a finding about the gene and the disease.
non-small cell lung carcinoma (48 papers, 2012 to 2025). A group of at least three distinct histological types of lung cancer, including non-small cell squamous cell carcinoma, adenocarcinoma, and large cell carcinoma. "It is reported that high BPA exposure in urine samples may be related to human non-small cell lung cancer via modifying ESR1 genetic polymorphism." (PMID 34311656, 2021). "In non-small cell lung cancer, ESR1 can be combined with EGFR, showing enhanced antiproliferation effects." (PMID 31905767, 2019). "Recent research has shown that cancers such as non-small cell lung cancer (NSCLC) also have very low-expression level of ESR1." (PMID 28302149, 2017). "ESR1 expression levels were shown to classify patients into groups with different prognoses in a study that analyzed gene expression data from patients with non-small cell lung cancer." (PMID 39457373, 2024). "This implies that ESR1 may function as a prognostic marker in non-small cell lung cancer in addition to influencing tumor biology." (PMID 39457373, 2024). "Overexpression of ESR1 m RNA is closely related to the prognosis of non-small cell lung cancer, while ESR1 is expressed in lung tissues of patients with COPD, but its specific mechanism remains unclear." (PMID 37274103, 2023). "ESR1/2 might directly or indirectly regulate oncogenic pathways in non-small-cell lung cancer, and FOXO1 expression is a favourable prognostic factor in non-small-cell lung cancer." (PMID 32457348, 2020). "The biological roles of estrogen receptor 1 (ERS1), estrogen receptor 2 (ERS2), and aromatase (CYP19A1) genes in the development of non-small cell lung cancer (NSCLC) is unclear, as is the use of their expression as a prognostic factor." (PMID 25310221, 2014).
glioma (46 papers, 2011 to 2026). A benign or malignant brain and spinal cord tumor that arises from glial cells (astrocytes, oligodendrocytes, ependymal cells). "A similar glioma patient’s prognosis classification was obtained when we measured ESR1 by immunohistochemical (IHC) staining on glioma samples." (PMID 38411438, 2024). "The mRNA expression levels of AKT1 and MAPK1 were relatively high in glioma, while those of RXRα, ESR1, and HSP90AA1 were relatively low." (PMID 38835342, 2024). "We also noticed that IDH‐mutant or IDH‐like LIHC and PRAD samples belonged to subtypes with low ESR1 expression, while high ESR1 subtype was exclusively IDH‐wild‐type in glioma (GBM and LGG), and the expression of ESR1 was lower in IDH1 mutated samples." (PMID 32536040, 2020). "Promoter hypermethylation at ESR1, expression of TRAF1 and mutations in NF-kB are all known to be associated with the emergence of glioma." (PMID 28957313, 2017). "We also find similar intermediary protein interactions through ESR1, AKT1 and SIRT1, whose activity are also associated with glioma." (PMID 28957313, 2017). "Stigmasterol, (S)-stylopine, isobrucine, icaride A, and isostrychnine N-oxide (I), which may act on key targets such as ADRB1, ADRB2, CHRM3, ADRA1A, and ESR1, are the main ingredients of semen strychni used to treat gliomas." (PMID 41430985, 2025). "Moreover, the expression of ESR1 correlated with overall survival in glioma (TCGA glioma diffuse cohort) and GBM TCGA cohort, but with an inverse correlation in Astrocytoma IDHmut, showing the same affectation as when we sub-grouped the patients by sex." (PMID 38411438, 2024). "Taken together, our results show a potential explanation for the poor prognosis observed in a group of men with low ESR1 levels, high necrosis, and an acute inflammation profile, which could have important implications for several aspects of glioma research and clinical practice." (PMID 38411438, 2024). "The top 5 main targets of semen strychni for the therapy of glioma were ADRB1, ADRB2, CHRM3, ADRA1A, and ESR1, based on the degree value of the software’s network function analysis." (PMID 41430985, 2025). "The potential top five genes of the anti-glioma effect of isocuB were identified by network pharmacology as RXRα, AKT1, ESR1, MAPK1, and HSP90AA1." (PMID 38835342, 2024). "The analysis revealed that the top five genes affected by isocuB in glioma were RXRα, AKT1, ESR1, MAPK1, and HSP90AA1." (PMID 38835342, 2024). "Only four genes differentially expressed in both LGG and GBM patients (ERBB1, RB1, ESR1, and KDR), indicating putative role in the regulatory of circadian rhythm pathway alteration in glioma." (PMID 34224318, 2021). "ESR1, detected by probe cg08415493, was also identified to participate in IDH-dependent glioma subtyping." (PMID 31803734, 2019). "Validation of DDX3X-regulated genes found that DDX3X protein highly expresses in human glioma cells and correlates the protein level of SP1, and ESR1." (PMID 26184164, 2015). "The DDX3X protein highly expresses in human glioma cells also correlates with the protein level of SP1, and ESR1 in human glioma cell lines including LN229, U87MG, GBM8401 and U118MG as compared with normal brain tissue." (PMID 26184164, 2015). "Based on this result, our study addressed the impact of ESR1 expression in the male GBM cohort to understand the reason for higher tumor aggressiveness in a subgroup of male patients compared to the rest of the males and all females with glioma." (PMID 38411438, 2024). "The core components of semen strychni used in the treatment of glioma included stigmasterol, (S)-stylopine, isobrucine, icaride A, and isostrychnine N-oxide (I), which may operate on core targets such as ADRB1, ADRB2, CHRM3, ADRA1A, and ESR1." (PMID 41430985, 2025).
schizophrenia (46 papers, 2010 to 2026). A major psychotic disorder characterized by abnormalities in the perception or expression of reality. "Candidate gene studies have further identified two ESR1 SNPs showing similar allele frequency and LD D’>0.5, associated with temperament and suicidal attempts (rs974276) and as a risk factor in schizophrenia (rs2273206)." (PMID 28617822, 2017). "For ESR1-203, levels were significantly lower in tissues homozygous for the main CC allele (p = 0.02), and for ESR1-008, levels trended to be higher in bipolar compared schizophrenia subjects in CT & TT carriers (p = 0.03)." (PMID 28617822, 2017). "Some SNPs in ESR1 were also found significantly associated with schizophrenia in our genotyping project (unpublished data)." (PMID 20156358, 2010). "ESR1 in schizophrenia has lower expressions in both related wild type and variants." (PMID 31086558, 2018). "A variant of the ESR1 gene has also been shown as a genetic risk factor for schizophrenia." (PMID 24618531, 2014). "ESR1 is the only TF in our network whose gene has positive association result for schizophrenia." (PMID 20156358, 2010). "Given the role of estrogen in the treatment of schizophrenia, we also examined sex hormone-related expression (AR, ESR1, ESR2, and PGR) in the brain." (PMID 38730231, 2024). "Of 1,183 genes that mapped to nominally significant DMPs, some were previously associated with BD or schizophrenia, including MLC1, ESR1, KCKN5, L1CAM, CPEB1 and GABBR2." (PMID 35922419, 2022). "It is suggested that the drugs which target ESR1 can be considered beside SSRIs in treatment of schizophrenia-OCD comorbidity or both disorders individually." (PMID 31086558, 2018). "Since EGR3 is a core gene in our miRNA-mediated schizophrenia network, this provides another link for ESR1 to schizophrenia." (PMID 20156358, 2010). "The core identified targets of aripiprazole include MAPK3 (mitogen-activated protein kinase 3), PPARG (peroxisome proliferator-activated receptor gamma), the D2 receptor, and ESR1 (estrogen receptor 1), providing new insights into the mechanisms of this drug in schizophrenia treatment." (PMID 40572510, 2025). "Recent studies show that it may be important in regulating the development of neuronal progenitor cells, and physically interacts with other schizophrenia susceptibility genes, such as CREB1, AKT1 and ESR1." (PMID 35576194, 2022). "Furthermore, females with schizophrenia have less severe deficits in cognitive parameters, such as memory, compared to males, and both miR-30B and ESR1 have been shown to be important for cognitive function." (PMID 29657307, 2018). "Therefore, the essential function of ESR1 brings out another relationship between schizophrenia and OCD in females." (PMID 31086558, 2018). "In conclusion, regulation of ESR1 may be critical point in schizophrenia patients with OCD incident." (PMID 31086558, 2018). "Therefore, we focus here on ESR1 variants affecting behavioral traits in neuropsychiatric disorders, including bipolar disorder, ADHD, and schizophrenia." (PMID 28617822, 2017). "Allelic expression imbalance of ESR1 mRNA was most pronounced in brain tissues from subjects with bipolar disorder and schizophrenia compared to controls, suggesting regulatory processes that change with disease status as a function of trans-acting factors, as observed previously." (PMID 28617822, 2017). "Parallel and multistep analysis in this research showed that SLC1A1, DRD2, DRD4, BDNF, ESR1, CDH2, GRIN2B, TNFa, GABBR1, and OLIG2 are common genes between schizophrenia and OCD which ESR1, DRD2, GABBR1, TNFa, and CDH2 are the most important individuals." (PMID 31086558, 2018). "Activity for ESR1 in decreased with the AKT inhibitor in the control sample, but increased with inhibitor in the schizophrenia sample." (PMID 28900113, 2017).
schizophrenia (continued). "Representative examples of kinase activity for reporter peptides ESR1 and NMDZ1 highlight the differential effects of kinase inhibitors on the control and schizophrenia samples." (PMID 28900113, 2017). "Since regulation of ESR1 expression appears to be contingent on multiple factors and disease states, we measured AEI in brain tissues from subjects diagnosed with schizophrenia and bipolar disorder, and from controls, using marker SNPs in expressed RNA isoforms." (PMID 28617822, 2017). "Here, we did not observe any sex-specific or sex-specific schizophrenia DEGs for sex hormone expression (AR [androgen receptor], ESR1 [estrogen receptor 1], ESR2 [estrogen receptor 2], and PGR [progesterone receptor]) across the brain." (PMID 38730231, 2024).
lung adenocarcinoma (43 papers, 1993 to 2026). A carcinoma that arises from the lung and is characterized by the presence of malignant glandular epithelial cells. "The relative transcript level of ERα (ESR1) was significantly higher in 621–101 cells (CT = 30.7) relative to lung adenocarcinoma A549 cells (CT = 36.4) (p < 0.001), although TSC2-reexpression (621–103 cells) did not affect ESR1 expression." (PMID 32078667, 2020). "The results showed that the mRNA expression levels of ESR1, DDX3X, MAPK10, KIT, FOXO1, and MCL1 were significantly lower in both lung adenocarcinoma (LUAD) and lung squamous cell carcinoma (LUSC) tissues (p < 0.001) than normal lung tissues." (PMID 38180107, 2023).
pancreatic cancer (43 papers, 2009 to 2026). "Studies in breast and pancreatic cancer cells indicated cell type-dependent activity of ESR1 harboring R269C." (PMID 32513126, 2020). "Our data suggest a role for R269C functional variant of the ESR1 in the development of a small subset of non-PDAC pancreatic cancers." (PMID 32513126, 2020).
neuroblastoma (42 papers, 2011 to 2025). Neuroblastoma (NB) is the most common solid, extracranial childhood tumor. "We and others recently showed that DKK3 and ESR1 as well as several TGFβ pathway components were down regulated as a result of increased levels of miRNAs encoded by the miR-17∼92 cluster in neuroblastoma." (PMID 23308108, 2013). "Molecular studies further support these findings, for example, MYCN-regulated microRNAs repress estrogen receptor-alpha (ESR1) expression and neuronal differentiation in human neuroblastoma." (PMID 41395311, 2025).
ductal carcinoma (41 papers, 2005 to 2025). "Ductal carcinomas showed low ESR1/PGR and PRLR gene expression as well, even though it has been shown that they have a low tendency to invade lymphatic vessel." (PMID 27649560, 2016). "Among the histological subtypes the lowest gene expression levels of ESR1, PGR and PRLR were found in solid, anaplastic and ductal carcinomas." (PMID 27649560, 2016). "Furthermore, the gene expression of ESR1, PGR and PRLR were significantly lower in solid, anaplastic and ductal carcinomas compared to the reference tissue." (PMID 27649560, 2016).
ductal carcinoma in situ (41 papers, 2005 to 2026). "However, we observed that SFRP1 overexpression in MCF10DCIS increased ESR1 expression, and then increased cell migration abilities in E2 conditions, while it decreased this expression in EtOH condition, suggesting that the role of SFRP1 in ERα-negative ductal carcinoma in situ could be E2-dependent." (PMID 37190179, 2023).
Hepatic steatosis (40 papers, 2015 to 2025). Steatosis is a term used to denote lipid accumulation within hepatocytes. "Previous studies demonstrated that hepatic steatosis occurred in Esr1 knockout mice but not in Esr2 deficient male mice." (PMID 40162312, 2025). "Furthermore, Esr1 knockout mice develop hepatic steatosis more often than their wild-type controls as a consequence of the increased expression of genes involved in de novo lipogenesis." (PMID 40162312, 2025). "The activation of the estrogen receptor gene (ESR1) could regulate hepatocyte factor, delay hepatic steatosis, and reduce IR for the sake of achieving the purpose of lowering blood glucose." (PMID 41476996, 2025).
invasive lobular carcinoma (40 papers, 2011 to 2026). "This has been explained by the greater propensity of invasive lobular carcinoma to have several genomic alterations which include phosphatidylinositol 3-kinases (PI3K) pathways and mutations in HER2, HER3 and estrogen receptor 1α(ESR1) genes, amongst other factors." (PMID 38338854, 2024).
ovarian tumors (39 papers, 2007 to 2025). "Given the correlation with ERα expression, we found elevated ESR1 levels in both ovarian tumor stroma and epithelial compartments compared to their respective normal counterparts." (PMID 30051594, 2018). "We found that GREB1 mRNA levels correlated with ESR1 in ovarian tumours, but GREB1 protein levels did not correlate with ESR1 in the TMA." (PMID 29973689, 2018).
leiomyoma (38 papers, 2009 to 2025). A well-circumscribed benign smooth muscle neoplasm characterized by the presence of spindle cells with cigar-shaped nuclei, interlacing fascicles, and a whorled pattern. "Our analyses indicated that among genes differentially expressed in leiomyomas, the PR is functionally linked to both ESR1 and sFRP4." (PMID 28637297, 2017). "In both tissues, downregulation of PGRB (2.5-fold p < 0.001, 3-fold p < 0.05 for myometrium and leiomyoma, respectively) and ESR1 mRNA (9-fold p < 0.001, 3-fold p < 0.01, for myometrium and leiomyoma, respectively) was observed when compared to T0." (PMID 35884847, 2022). "According to chromosomal interaction data, rs58415480 and rs71575922 are candidate regulators of seven target genes including ESR1, which is important in the growth of leiomyomas." (PMID 30194396, 2018). "Both, in culture of isolated human leiomyoma cells, and in culture of whole tissue pieces preserving the characteristic extracellular matrix, ESR1 and PGR mRNA are strongly downregulated within hours." (PMID 26588841, 2015). "ST image showed that the expression of ESR1 was mainly distributed in the tissue of leiomyoma." (PMID 37215998, 2023). "ST image showed that the expression of ESR1 was highly distributed in the tissue of leiomyoma, indicating ERα might mediate the development of uterine leiomyoma." (PMID 37215998, 2023). "In addition, we found that the leiomyomas that developed in the G12V mice were hypercellular and highly mitotic according to Ki-67 staining and ESR1-positive." (PMID 33244099, 2020). "Leiomyoma is ESR1 positive and very responsive to estrogen stimulation." (PMID 33244099, 2020). "Hypomethylation of ESR1 in leiomyoma was reported using a group of Japanese subjects; thus the difference between our findings and theirs could be attributed to racial differences." (PMID 22428009, 2012). "ESR1, estrogen receptor 2 (ESR2) and PGR were significantly up-regulated in endothelial cells of leiomyoma compared to pseudocapsule." (PMID 37215998, 2023). "Here, both snRNA-seq and ST results showed that ESR1 and PGR were expressed higher in leiomyoma than these in pseudocapsule and myometrium." (PMID 37215998, 2023). "The steroid hormone receptors, ESR1 and PGR, and smooth muscle cell markers were expressed at the same level in LMSP, LMMP, and cultured cells from whole leiomyoma tissue." (PMID 22570742, 2012). "We were also able to confirm that levels of DARC (P < 0.05), SLC2A5 (P < 0.05), ID3 (P < 0.02), LRNF5 (P < 0.01), UGT8 (P = 0.04), ESR1 (P < 0.01), and PGR (P < 0.01) were significantly lower when luteal phase leiomyomas were compared with proliferative phase leiomyomas." (PMID 28637297, 2017). "Upregulation of ESR1, PGR and aromatase in leiomyoma tissue were reported." (PMID 22570742, 2012). "We particularly paid attention to the ESR1 gene, but we did not observe any differential DNA methylation patterns between leiomyoma and myometrium." (PMID 22428009, 2012).
postmenopausal osteoporosis (38 papers, 2010 to 2025). Metabolic disorder associated with fractures of the femoral neck, vertebrae, and distal forearm. "In a study examining the relationship between ESR1 gene variants and postmenopausal osteoporosis in the Chinese population, it was reported that only the ESR1 rs9340799 (XbaI) variant was related to postmenopausal osteoporosis." (PMID 40332270, 2025). "The association between ESR1 gene variants and postmenopausal osteoporosis has been widely studied, but findings are conflicting." (PMID 40332270, 2025). "For example, estrogen receptor modulators/agonists targeting ESR1 are now used in the clinic; this includes bazedoxifene acetate and conjugated estrogens for preventing postmenopausal osteoporosis (related to oestrogen deficiency)." (PMID 35401535, 2022).